HOTAIR (HOX transcript antisense RNA)
Diseases named in the same sentence as HOTAIR in open-access papers (continued):
Sharing a sentence is not in itself a finding about the gene and the disease.
breast cancer (continued). "HOTAIR promotes the EMT and also induces the transcription of vascular endothelial growth factor (VEGF), facilitating in this way the angiogenesis and breast cancer progression." (PMID 39285617, 2025). "Recent studies have shown that small molecule inhibitors that block certain sequences where HOTAIR interacts with PRC2 or LSD1, as well as the interactions between PRC2 and LSD1, can inhibit breast cancer cell metastasis." (PMID 40234937, 2025). "HOTAIR further controls the Suv39H1-mediated AKT/mTOR signaling thanks to its sponge activity for miR-130a-3p, thus promoting invasion and metastasis of breast cancer cells." (PMID 37308974, 2023). "Therefore, HOTAIR may be a potential therapeutic target in breast cancer." (PMID 36924407, 2023). "The expression of HOTAIR was higher in MDA-MB-231 than in MCF-7; thus, we selected a highly invasive breast cancer cell line, MDA-MB-231 (a type of TNBCcells), for cell transfection in the subsequent experiments." (PMID 36233075, 2022). "Compared with the normal mammary cells, the qRT-PCR showed that HOTAIR was upregulated while MAPT-AS1, EGOT, and SEMA3B-AS1 were downregulated in breast cancer cells." (PMID 35990656, 2022). "HOTAIR is a lncRNA that induces migration and invasion of TNBC cell lines and was the first lncRNA to act as a marker of metastasis, also in breast cancer." (PMID 35076579, 2022). "HOTAIR, the HOX antisense intergenic lncRNA, is known to function in normal cell development, and the overexpression of HOTAIR leads to breast cancer development." (PMID 35853961, 2022). "For example, LSINCT5 and Zfas one can promote the proliferation of breast cancer, HOTAIR suppresses invasion and migration of breast cancer, SOX2OT induces SOX2 expression in breast cancer, and SRA is the expression activator of breast cancer." (PMID 36744179, 2022). "Overall, our work provides insight into mechanisms of how m6A regulates HOTAIR-mediated breast cancer metastasis which could ultimately lead to new strategies (for example, preventing m6A methylation at this specific site) to prevent or reverse the effects of elevated HOTAIR in breast cancer." (PMID 36441764, 2022). "Recently, a computer-aided structure-based drug design method has been able to develop small molecule inhibitor of HOTAIR (e.g., AC1NOD4Q) which particularly interferes with the HOTAIR/EZH2 interaction and prevents tumor metastasis in breast cancer models." (PMID 35755302, 2022). "Furthermore, high expression of HOTAIR in BC patients is strongly correlated with lymph node metastasis, recurrent and poor prognosis of breast cancer." (PMID 35864503, 2022). "Downregulation of HOTAIR and EZH2 and H3K27me3 expression with Dp resulted in upregulation of miR-34a in breast cancer cells and MNU-treated rats." (PMID 35369062, 2022). "In breast cancer, modulation of several lncRNAs contribute to the stemness phenotype, including well-known non-coding RNAs such as MALAT-1, HOTAIR and H19." (PMID 35626715, 2022). "However, liquid biopsy studies did not evidence specific associations between HOTAIR levels and receptors status, suggesting that circulating HOTAIR might represent a powerful liquid biopsy biomarker for breast cancer independently from the subtype." (PMID 35076579, 2022). "HOTAIR function is particularly striking in MDA-MB-231 cells, given that this is already a highly invasive breast cancer cell line, and its invasiveness is increased even further by HOTAIR overexpression." (PMID 36441764, 2022). "Therefore, HOTAIR may regulate breast cancer progression by controlling the miR-601/ZEB1 axis." (PMID 35328609, 2022). "Reduced expression of BLACAT1 in HNSCC; MALAT1, NEAT1 and PVT1 in NPC; FAM201A, PVT1 and LINC00857 in NSCLC; LINC00473, CCAT2and Rpph1 in EC; HOTAIR and LINC00958 in CRC; AFAP1-AS1 and LINC00511 in breast cancer were correlated with radiosensitivity." (PMID 36323697, 2022).
breast cancer (continued). "The anticancer effects of Dp-3-G were due to suppression of Akt stimulation and enhanced IRF1 expression which are involved in controlling HOTAIR expression in carcinogen treated MCF10A, other breast cancer cells and in xenografted breast tumor." (PMID 35369062, 2022). "For example, MALAT1, HOTAIR, lincRNAp21, GAS5, TUG1, and ncRNA-CCND1 were identified in EVs derived from human cervical and breast carcinomas." (PMID 35250537, 2022). "In breast cancer, multiple lncRNAs played an important role in the regulation of TRAIL, like HOTAIR, NEAT1, BCAR4 and DSCAM-AS1." (PMID 34282054, 2021). "In breast cancer, TGF-β1 secreted by CAFs up-regulates HOTAIR expression to promote epithelium- mesenchyme transition (EMT) and metastasis." (PMID 34123857, 2021). "We conclude that HOTAIR over-expression behaves as a positive regulator of cell growth and migration both in normal and DCIS breast cells involved with early-stage breast cancer progression." (PMID 34869037, 2021). "Univariate and multivariate logistic regression analyses were carried out to assess the predictive values of PVT1, MALAT1, NEAT1, HOTAIR, PAI-1, and OPN in breast cancer." (PMID 33670447, 2021). "HOTAIR is expressed by a sequence within the highly conserved HOX gene, which has been found to be highly expressed in multiple tumors, including breast cancer, ovarian cancer, esophageal cancer, and colorectal cancer." (PMID 33747903, 2021). "Serum levels of HOTAIR, PAI-1, and OPN were shown to be significant predictor variables of fibroadenoma progression to breast cancer in both the univariate analysis and the multivariate analysis." (PMID 33670447, 2021). "In the present study, we also measured the serum expression levels of HOTAIR, MALAT1, and NEAT1 as possible biomarkers of breast cancer." (PMID 33670447, 2021). "The serum levels of HOTAIR, PAI-1, and OPN were significantly higher in breast cancer patients compared to controls and fibroadenoma patients." (PMID 33670447, 2021). "Serum HOTAIR level was found to be positively correlated with NEAT1 and MALAT1 levels in the breast cancer patients (r = 0.35, p < 0.05 and r = 0.51, p < 0.001, respectively)." (PMID 33670447, 2021). "For example, HOTAIR is a ceRNA for miR-206 and increases the expression of a miR-206 target gene, the Bcl-w/Bcl-2 like protein 2 (BCL2L2) gene, thus promoting breast cancer proliferation." (PMID 32486413, 2020). "We have previously demonstrated that under hypoxic conditions HIF-1α expression was downregulated by miR-204 mimics in breast cancer cells which could explain, in part, the negative effects of miR-204 we found in hypoxia-induced vasculogenic mimicry associated with HOTAIR upregulation." (PMID 32466537, 2020). "HOTAIR, HBXIP, and LSD1 promote breast cancer proliferation, highlighting the function of HOTAIR as a critical effector of c-Myc in cooperation with HBXIP and LSD1." (PMID 32486413, 2020). "Adding to this, disrupted expression level of RBM38 in breast cancer due to the silencing E-box element promoter region by SNAIL, propose the indirect effect of HOTAIR on regulation of this tumour suppressor gene." (PMID 32245498, 2020). "Using two different experiments, it has been demonstrated that HOTAIR activity reduced radiosensitivity of MB231 and SKBR3 breast cancer cell lines by down-regulation of the HOXD10 tumour suppressor gene and the corresponding pathway, PI3K/AKT-Bad." (PMID 32245498, 2020). "HOTAIR, in turn, activates the EMT, migration, and invasion of breast cancer cells by the epigenetic suppression of EGR1 and CDK5RAP1 promoters." (PMID 33050576, 2020). "Many studies have indicated that several lncRNAs, such as HOTAIR, linc-ROR, and BCAR4, are upregulated and they promote breast cancer invasion and metastasis." (PMID 32929060, 2020). "HOTAIR, the most studied lncRNA, interacts with 26 various functional elements, such as EZH2 and PCBP1, and 40 diseases, including gastric cancer, breast cancer and colon cancer." (PMID 30759219, 2019).
breast cancer (continued). "Overexpression of HOTAIR and methylation of HOXA5 were also observed in the progression of breast cancer." (PMID 31168296, 2019). "HOTAIR mediates H3K27 tri-methylation with consequent silencing of tumor suppressors in many cancer types, including breast cancer, where it is reported to promote drug resistance and cancer stemness." (PMID 30927908, 2019). "It has been previously reported that the lincRNA HOTAIR mediates recruitment of polycomb repressive complex 2 (PRC2) leading to aberrant transcriptional silencing of tumor suppressor genes in glioma and breast cancer." (PMID 31367244, 2019). "Through a ceRNA mechanism, HOTAIR inhibits miR-7 and regulates the EMT of breast cancer stem cells by down-regulating the STAT3 Pathway." (PMID 30429228, 2019). "In this study, our experiment demonstrated that CAFs upregualted HOTAIR expression via TGF-β1 secretion, supporting its importance in breast cancer progression." (PMID 29325547, 2018). "HOTAIR can also indirectly suppress certain miRNA expressions in TNBC, reverse epithelial‐mesenchymal transition (EMT) partially, decrease the breast cancer stem cell population, and attenuate cell metastasis and invasion." (PMID 28941134, 2018). "This notion is appealing because HOXC11 promotes breast cancer and the importance of PRC2 to HOTAIR functions has been challenged recently." (PMID 28846832, 2017). "HOTAIR expression is necessary for maintenance of the CSC phenotype in colon and breast cancer cell lines." (PMID 28872613, 2017). "Oestrogen increases HOTAIR levels via GPER-mediated miR-148a inhibition and is an independent prognostic marker of metastasis in breast cancer." (PMID 28738804, 2017). "For HOTAIR and DSCAM-AS1, such experiments to examine their oncogenic roles were carried out in breast cancer cell lines." (PMID 28738804, 2017). "In a similar vein, HOTAIR was found to be essential to the induction of EMT by TGF-β1 in colon cancer and breast cancer cells." (PMID 28430163, 2017). "Both HOTAIR and EZH2 showed a higher expression level in primary breast cancer samples than metastases." (PMID 29469819, 2017). "Previously, it was reported that HOTAIR was required for EMT and stemness maintenance in colon and breast cancer cell lines." (PMID 29228709, 2017). "HOTAIR competes with BRCA1, a critical protein in breast cancer and is a critical regulator of genes involved in epithelial-to-mesenchymal transition." (PMID 29469819, 2017). "It therefore should be of concern that HOTAIR expression is induced by nanomolar concentrations of xenoestrogens/xenobiotics (bisphenol-A, BPA or diethylstibestrol, DES) in human breast cancer cells in vitro and in rat mammary glands in vivo." (PMID 28587163, 2017). "Upon E2, a significant increase of HOTAIR and MALAT1 transcripts was observed in breast cancer, PCa and benign prostate hyperplasia (C17IM) cells." (PMID 27922078, 2016). "However, the mechanism by which HOTAIR increases in breast cancer is unknown." (PMID 25928008, 2015). "HOTAIR, binds physically to the chromatin modifying enzymes PRC2 and LSD1 to reprogram the chromatin state and further promote cancer metastasis in breast cancers and colorectal cancers, also exhibits oncogenic activity in ESCC." (PMID 26158411, 2015). "GRER mediates E2-induced HOTAIR levels in breast cancer cells, and E2/GPER promote HOTAIR levels through miR-148a." (PMID 25928008, 2015). "According to the lncRNADisease Database, there are 16 lncRNAs known to play a role in breast cancer including H19, growth arrest-specific 5 (GAS5), homeobox antisense intergenic RNA (HOTAIR), and breast cancer anti-estrogen resistance 4 (BCAR4)." (PMID 25849966, 2015). "HOTAIR, a lincRNA in the mammalian HOXC locus, was the first lincRNA that was found to be systematically dysregulated during breast cancer progression via microarray analysis." (PMID 26448942, 2015).
breast cancer (continued). "HOTAIR has been shown to inhibit tumor suppressor genes such as HOXD10, PGR, and the proto-cadherin gene family in breast cancer cells." (PMID 25405331, 2015). "β-catenin expression is known to be a poor prognosis marker in breast cancer and its activation has been correlated with TNBC, further suggesting a correlation between HOTAIR expression and TNBC." (PMID 25883211, 2015). "In fibroblasts HOTAIR represses HOXD8-D11 by recruiting PRC2 and an inverse relationship between HOTAIR and HOXD10 was reported in breast cancer." (PMID 25994132, 2015). "We chose posterior HOXC genes HOXC11-13 located in close proximity to the HOTAIR transcript and posterior HOXD genes HOXD10-13, reported to be regulated by HOTAIR in normal fibroblasts and breast cancer mediating aggressive phenotype." (PMID 25994132, 2015). "However, it is unknown how HOTAIR is regulated in TN breast cancer." (PMID 25928008, 2015). "An intriguing observation in breast cancer tissues is that increased DNA methylation in an intergenic CpG island located between HOXC12 and HOTAIR is positively correlated with HOTAIR expression in breast cancer." (PMID 25491133, 2014). "LncRNA expression is de-regulated in many types of cancers, such as HOTAIR in breast tumours and metastases, BACE1-AS in Alzheimer's disease and Gas5 in breast cancer." (PMID 25025236, 2014). "HOTAIR regulates the chromatin methylation state by inducing genome-wide retargeting of PRC2 and promotes metastasis of breast cancer by silencing multiple metastasis-suppressing genes." (PMID 25303230, 2014). "HOTAIR was also shown to induce epithelial-to-mesenchymal transition (EMT) following TGF-β1 treatment in colon and breast cancer cell lines." (PMID 24971229, 2014). "We next performed qRT-PCR analysis to examine the expression levels of HOTAIR in various cancer cell lines, including gastric, non-small cell lung cancer (NSCLC) and breast cancer-derived cells." (PMID 24775712, 2014). "As expected, our bioinformatic approach validated previous observations such as the link between HOTAIR expression and the PRC2 complex in breast cancer, giving us confidence in our methodology." (PMID 25296969, 2014). "In our experiments, we detected HOTAIR and NEAT2 RNAs simultaneously with the telomeric DNA regions in human breast cancer cells." (PMID 25226542, 2014). "Subsequent studies suggested HOTAIR induced genome-wide retargeting of PRC2, leading to H3K27me3, and promoted metastasis of breast cancer by silencing multiple metastasis suppressor genes." (PMID 23717443, 2013). "This study indicates that HOTAIR and PRC2 complex specifically act through silencing of metastasis suppressor genes and alteration of the epigenetic program of breast cancer cells to promote cancer progression and metastasis." (PMID 21915889, 2011). "They demonstrated a combined role of HOTAIR and PRC2 complex in breast cancer invasiveness via overexpression and knock down of HOTAIR and PRC2 components through in vitro and in vivo studies." (PMID 21915889, 2011). "Similar to HOTAIR, AIRN recruits the histone modifying complex PRC2 potentially mediating gene silencing in NK cells and affecting its antitumor activity in breast cancer patients." (PMID 40781182, 2025). "Therefore, this study aims to investigate the expression patterns and potential regulatory relationships between key transcription factors (FOXC2, SNAIL, and ZEB) and oncogenic lncRNAs (HOTAIR, MALAT1, and UCA1) in metastatic breast cancer stem cells." (PMID 40781106, 2025). "This study aimed to explore the molecular pathways connecting the long non-coding RNAs (lncRNAs) HOTAIR, UCA1, and MALAT1 with breast cancer stem cell-related genes FOXC2, SNAIL, and ZEB, focusing on their involvement in transcriptional regulation, proliferation, and survival." (PMID 40781106, 2025). "To date, no information has been reported about how lncRNA HOTAIR exerts its involvement in breast cancer chemoresistance." (PMID 39925739, 2025).
breast cancer (continued). "HOTAIR has been identified as a promising biomolecule for noninvasive prognostic biomarker and targeted therapies in breast cancer." (PMID 40686703, 2025). "Furthermore, exosomal lncRNA HOTAIR, UCA1 and H19 in drug-resistant breast cancer and exosomal lncRNA UCA1 in drug-resistant ovarian cancer seem to be promising diagnostic biomarkers and molecular targets to reduce drug resistance." (PMID 39925739, 2025). "In treating human breast cancer cells, calycosin (0.5–100 μM) diminished Akt phosphorylation and reduced PI3K/Akt pathway activation, which results in the downregulation of HOTAIR expression, leading to control proliferation, invasion, and migration and inhibits apoptosis." (PMID 38230908, 2024). "For example, the upregulation of HOTAIR can activate FGFR and Wnt/β-catenin signaling pathways to promote epithelial–mesenchymal transition (EMT) and inhibit the Akt/JNK signaling pathway, facilitating invasiveness and metastasis in breast cancer." (PMID 38374003, 2024). "lncRNA HOTAIR acts as a molecular sponge of miR‐20a‐5p and, as ceRNA, it affects the activity and regulates the miR‐20a‐5p target genes, like HMGA2, thus contributing to breast cancer (BC) development and tumorigenesis." (PMID 37143733, 2023). "Hence, lncRNAs, such as DANCR, HOTAIR, H19, and GAS5, are identified as key regulators of autophagy in breast cancer, and further research needs to be carried out to identify their potential in breast cancer diagnosis and treatment." (PMID 36899946, 2023). "The induction of HOTAIR expression after TGF-β1 treatment was further described by Padua Alves and Colleagues as a requirement for the EMT induction and the maintenance of stem properties of colon and breast cancer cells." (PMID 37308974, 2023). "Similarly, the metformin-regulated expression of MALAT1, HOTAIR, and TUG1 was reported to be upregulated in breast cancer cells." (PMID 38053839, 2023). "In addition, it has been reported that propofol inhibits cervical cancer progression by regulating the HOTAIR/miR-129-5p/RPL14 axis and HOTAIR promotes breast cancer progression by regulating the miR-129-5p/FZD7 axis." (PMID 36115953, 2022). "In this study, we present a new mechanic through bioinformatics tool and basic experiments: the HOTAIR/miR-203/CAV1 axis, which complemented the role network of HOTAIR as a ceRNA, thus, it will provide a novel potential idea for breast cancer research and therapy." (PMID 36233075, 2022). "Although HOTAIR has been shown to have an oncogenic role in breast cancer cells, to our knowledge, an unbiased screen of the HOTAIR interactome has not yet been performed in a breast cancer cell line." (PMID 35087108, 2022). "Moreover, suppressing HOTAIR in combination with other epigenetic drugs (e.g., DZNep and AC1Q3QWB) showed a great promise in treatments for breast cancer and glioblastoma." (PMID 35755302, 2022). "Finally, the role of the HOTAIR/miR-203/CAV1 axis in the proliferation, invasion, and migration of the breast cancer cell line MDA-MB-231 was clarified." (PMID 36233075, 2022). "Gene array studies revealed the minimal overlap of genes regulated by HOTAIR between PC and breast cancer cells, and further research using EZH2 knockdown and chromatin immunoprecipitation demonstrated that gene repression mediated by HOTAIR was both PRC2-dependent and PRC2-independent." (PMID 35565245, 2022). "We also measured the growth curve of iHOT+ cells under these same three conditions and found that HOTAIR expression levels do not affect proliferation of iHOT+ breast cancer cells." (PMID 36579891, 2022). "Our work also shows that, rather than degradation of HOTAIR, m6A sites in HOTAIR mediate its high expression in breast cancer via YTHDC1." (PMID 36441764, 2022). "HOTAIR (Hox transcript antisense intergenic RNA) is one of these lncRNAs transcribed from the HOXC locus and is able to reprogram chromatin state to promote cancer metastasis in breast cancers at its first discovery." (PMID 36273585, 2022).